IL13 (interleukin 13)
Diseases named in the same sentence as IL13 in open-access papers (continued):
Sharing a sentence is not in itself a finding about the gene and the disease.
asthma (continued). "Exploring gene targets of miR-499a by computational tools identified inflammatory-related gene targets, including IL-13 and Il-23, which represent important mediators in asthma KEGG pathway [ID hsa05310] (microRNA.org)." (PMID 28886711, 2017). "The Th2-derived cytokines, IL-4, IL-5, IL-9, and IL-13 mRNA expression was also markedly increased in the patients with severe asthma patients with CRS." (PMID 28199345, 2017). "In patients with this asthma phenotype, lebrikizumab, a monoclonal antibody to IL-13 is effective in improving lung function." (PMID 28704401, 2017). "In particular, nasal IL-5 and IL-13 are upregulated in asthma versus controls, especially on days 3–5, and this confirms the greater induction demonstrated in terms of changes from baseline in asthmatic compare to healthy subjects." (PMID 28373098, 2017). "For instance, in a murine model of Sendai-induced para-influenza, despite clearing the infection, mice progressed to develop an asthma-like disease mediated by sustained activity of NK T cells driving macrophages to produce interleukin-13 (IL-13)." (PMID 28954232, 2017). "Tralokinumab is an IL-13 specific human immunoglobulin G4 monoclonal antibody that binds to and neutralizes IL-13, which showed therapeutic advantage in clinical trials involving patients with asthma and idiopathic pulmonary fibrosis." (PMID 28934123, 2017). "Another family member, FOXA3, also functions as a goblet cell metaplasia regulator: it is highly expressed in patients with asthma, and is IL-13- and rhinovirus-inducible." (PMID 29186064, 2017). "Similar to asthma, AD, and EoE, it is believed that IL-4 and IL-13 play important roles in the pathophysiology of ECRSwNP." (PMID 29034234, 2017). "We and others previously found that pendrin/SLC26A4, an anion transporter located at the apical side of airway epithelial cells, is a downstream molecule of the IL-4/IL-13 signals that plays an important role in the pathogenesis of asthma." (PMID 29359006, 2017). "Asthma is characterized by type 2 immune responses and production of cytokines such as IL-4, IL-5 and IL-13 that drive the allergic disease." (PMID 28830530, 2017). "We considered the possibility that cigarette smoke also likely modulates epithelial gene expression induced by cytokines other than IL‐13 that are known to be increased in asthma, such as IL‐17." (PMID 28701525, 2017). "The IL-13 transcriptional “signature” can be used to identify individuals with “Th2 high” and “Th2 low” asthma." (PMID 28057889, 2017). "The stratification of patients in clinical trials based on specific endotypes has lent support for continued efforts to modify IL-4 and IL-13 pathways in type-2-high asthma, yet additional variation in treatment response is still apparent." (PMID 28721208, 2017). "IL-13 is one of the key mediators in the pathogenesis of asthma; thus, inhibition of IL-13 by tralokinumab offers a rational approach to the treatment of this disease." (PMID 28590244, 2017). "This was a post hoc analysis carried out in a subset of patients from two independent Phase 2 studies and therefore will require further validation to better understand the role of IL-13 in the number and activation status of eosinophils in asthma." (PMID 29034234, 2017). "Of note and similar to therapies targeting the IL-13 pathway in asthma, these trials reported elevated blood eosinophil levels in patients treated with dupilumab compared to placebo." (PMID 29034234, 2017). "In vivo, they found less expression of let-7 in OVA-induced asthma mice model, and when let-7 mimic was delivered into these mice, a reduction of IL-13 and other asthma features such as cell infiltration and AHR were observed." (PMID 28785260, 2017). "In humans, blocking receptors for IL-4 and IL-13 improves lung function and reduces the frequency of exacerbations in individuals with moderate-to-severe asthma with high levels of eosinophils." (PMID 28670318, 2017).
asthma (continued). "Future studies in mild and moderate asthma will inform as to the extent to which the IL13 disease signature is evident in the peripheral airways throughout the entire spectrum of this disease and its relationship to disease control." (PMID 28045928, 2017). "Current studies have identified that target IL-13 pathway is a promising therapeutic approach for asthma." (PMID 28057889, 2017). "Here, we provide a perspective on the role of IL-13 in asthma and other eosinophilic disorders and describe ongoing clinical trials targeting this pathway in patients with significant unmet medical needs." (PMID 29034234, 2017). "This gene set includes numerous cytokines that mediate Th2 cell signaling associated with asthma (IL3, IL4, IL5, IL9, IL10 and IL13), as well as components of the IgE receptor (FCERA, FCERG, MS4A2) and eosinophil granule proteins (ECP, EDN, EPX, and MBP)." (PMID 28854632, 2017). "In this study, ITLN-1 was induced by IL-13 and mainly expressed in goblet cells of the distal and proximal airways in SN-Asthma patients." (PMID 28775743, 2017). "SPDEF expression is increased in airway epithelial cells of patients with asthma compared with healthy controls, remains increased in spite of anti-inflammatory treatment, and is upregulated following IL-13 stimulation." (PMID 29186064, 2017). "In conclusion, our results indicate that CS differentially affects the IL‐13‐induced expression profile including the recently described epithelial 3 gene signature for Th2‐high asthma." (PMID 28701525, 2017). "Mice that lack key Th2 cytokines such IL-4 or IL-13 had substantial reductions in asthma features in the OVA model." (PMID 28670318, 2017). "For example, a recent trial with anti-IL-13 (lebrikizumab) demonstrated improved airflow (prebronchodilator FEV1) in patients with type 2 high asthma." (PMID 29186064, 2017). "Once activated, ILC2s release IL-4 and IL-13 that are main keys to the inflammatory features on asthma." (PMID 28670318, 2017). "We and others previously found pendrin/SLC26A4 as a downstream molecule of IL-13, a signature type 2 cytokine critical for asthma, and showed its significance in the pathogenesis of asthma using model mice." (PMID 29359006, 2017). "CLCA1 and SERPINB2 were upregulated in severe asthma and also in peripheral airways suggesting the persistence of the IL-13 signature in this lung region." (PMID 28045928, 2017). "While these data are potentially interesting and begin to shed light on the relationship between IL-13 and eosinophils in asthma there are some caveats." (PMID 29034234, 2017). "In conclusion, we found IL-13 to be critically involved in the development of chemical-induced asthma, as shown here by using IL-13 KO mice, and more specifically in the effector phase as confirmed by anti- IL-13 antibody treatment." (PMID 28704401, 2017). "IL-13 exacerbates IL-5-triggered asthma, and overexpression of IL-13 in the intestinal tract induces inflammatory bowel disease and causes lesions of the endothelium, which eventually lead to arteriosclerosis and other cardiovascular dysfunctions." (PMID 29292401, 2017). "In this study, ITLN-1 mRNA significantly correlated with FeNO and serum IgE, as well as iNOS, CCL26, periostin and DPP4 mRNA in SN-Asthma, as these genes are known to be induced in BECs stimulated with IL-13." (PMID 28775743, 2017). "In addition, other IL-13 polymorphisms might be associated with asthma risk as well." (PMID 28057889, 2017). "The results showed that treating asthma mice with TT significantly suppressed the levels of IL-4 and IL-13, and increased the IFN-γγ levels in the BALF, as compared with the data of asthma mice treated with ST." (PMID 28769099, 2017). "Th2 cytokines (IL-4, IL-5, and IL-13) are known to be critically involved in the pathogenesis of asthma." (PMID 28746467, 2017).
asthma (continued). "Additional control of Th2 inflammation can be achieved in select asthma patients with biologic therapies such as anti-IL-5 and anti-IL-13 antibodies, which have also been trialed in EoE." (PMID 28831387, 2017). "S1P is suggested to contribute to airway hyperreactivity and release of IL-4 and IL-13, thereby involving in asthma pathogenesis." (PMID 28659663, 2017). "Periostin is reported to be the most robust biomarker predicting the effectiveness of lebrikizumab, an anti-IL-13 antibody, for treating asthma." (PMID 28219384, 2017). "The results showed that the expression of miR-98 was higher in the peripheral B cells of asthma patients, which mediated the effects of IL-13 on suppression of TSP1 in B cells." (PMID 28760845, 2017). "The main pathophysiological characteristics of asthma are due to proinflammatory factors (for example, IL-4, IL-5, and IL-13) that are released by many immune cells." (PMID 29311962, 2017). "OVA-IgE, IL-4, IL-5, IL-13 and INF-gamma in BALF was also increased in TLR2-deficient mice treated with B7-H3, which suggest in OVA-induced asthma model B7-H3 augment the inflammatory response independent of TLR2 pathway." (PMID 28094276, 2017). "Dupilumab, a humanized monoclonal antibody to IL-4Rα that inhibits both IL-4 and IL-13 signaling, is being assessed in patients with uncontrolled asthma." (PMID 29034234, 2017). "One study comparing PBMC methylation changes of 97 inner-city children with persistent atopic asthma to 97 healthy controls found 81 differentially methylated regions, including hypomethylated immune genes in asthma (i.E. il13, RUNX3, TIGIT)." (PMID 28774304, 2017). "In patients with asthma, where airway function is deteriorated and inflammatory responses are induced, high IL-13 levels have been observed in BALF and lung." (PMID 28243240, 2017). "Th2 lymphocytes play a critical role in the initiation and progression of allergic diseases, including atopic dermatitis and asthma, by releasing IL-4, IL-5, and IL-13." (PMID 29062168, 2017). "Using this assay, we found significantly higher levels of serum IL-13 in severe asthma patients relative to healthy volunteers and these levels strongly correlated with the type 2 gene signature in bronchial epithelium." (PMID 29034234, 2017). "Tralokinumab, a human IL-13 neutralizing monoclonal IgG4 antibody, has been tested in patients with uncontrolled asthma, ulcerative colitis, and rapidly progressive idiopathic pulmonary fibrosis." (PMID 29155876, 2017). "For instance, in a murine model of Sendai-induced para-influenza, despite clearing the infection mice progressed to develop an asthma-like disease mediated by sustained activity of natural killer T cells driving macrophages to produce interleukin-13." (PMID 29073216, 2017). "CD8α+ DCs enhance cross-priming of CD8+ T cells redirecting the immune response in asthma away from Th2 response, as shown here with decrements of IL-4 and IL-13 levels, decreased number of eosinophils." (PMID 28670318, 2017). "IL-12p40 (p = 0.005), IL-13 (p = 0.04), IL-1β (p = 0.02), and IL-4 (p = 0.03) were increased in those with Easy-to-Control asthma." (PMID 28686637, 2017). "A persistent disease signature associated with IL-13 (CLCA1, POSTN, SERPINB2) was identified in peripheral airways in treatment-resistant severe asthma." (PMID 28045928, 2017). "Recently serum periostin, a matricellular protein generated by airway epithelial cells and partly regulated by IL-13, has been proposed as a biomarker with a potential clinical role in severe asthma." (PMID 28194189, 2017). "The results of these studies should shed significant light on the relationships between IL-13 and airway eosinophilia and other pathologies in asthma patients in vivo." (PMID 29034234, 2017). "It has been demonstrated in mice models that IL-13 impaired antiviral immune responses in various respiratory diseases including asthma and chronic obstructive pulmonary disease (COPD)." (PMID 28900378, 2017).
asthma (continued). "Inhalation of an ASO targeting Mex-3B suppressed airway eosinophilia, lung inflammation, mucus hypersecretion, and BAL fluid levels of Th2 cytokine IL-4, IL-5 and IL-13 in an experimental model of asthma." (PMID 28106744, 2017). "The association of IL-13 with asthma pathology and reduced corticosteroid sensitivity suggests a potential benefit of anti-IL-13 therapy in refractory asthma." (PMID 28057889, 2017). "In mouse models of asthma induced by diisocyanates, a group of known chemical asthmogens, it has been shown that both Th2 and Th1 cytokines, including IL-13, IL-4 and IFN-γ, are associated with the development of asthma features." (PMID 28704401, 2017). "IL-13 is closely related to IL-4, which binds to IL-4R receptors and is also expressed by Th2 cells from asthma patients." (PMID 28570692, 2017). "Further investigation is also required to definitively address what are the consequences, if any, of increased blood eosinophils in asthma patients in response to anti-IL-13 therapies." (PMID 29034234, 2017). "Other researchers have also compared the relationship between ILC2s and asthma control status, and the results indicate a positive correlation between IL-13-producing ILC2s and asthma control status." (PMID 28271447, 2017). "ITLN-1 is induced by IL-13 and expressed mainly in goblet cells in untreated asthma where its levels correlate with known Type-2 related parameters." (PMID 28775743, 2017). "A number of analyses using asthma model mice have established the significance of IL-4 and/or IL-13, particularly the latter, in the pathogenesis of asthma." (PMID 29359006, 2017). "IL-13 is a pleiotropic type 2 cytokine that has been shown to be integral in the pathogenesis of asthma and other eosinophilic disorders." (PMID 29034234, 2017). "IL-13 is a pleiotropic type 2 cytokine that has been shown to be important in the pathogenesis of asthma and other eosinophilic disorders." (PMID 29034234, 2017). "Mirroring these decreases, we found that asthma and IL-13 downregulated BPIFA1 mRNA and intracellular protein levels." (PMID 28165446, 2017). "In Th2‐mediated asthma, goblet cell metaplasia and associated MUC5AC overexpression are mainly attributed to the presence of IL‐13." (PMID 28701525, 2017). "O. humifusa effectively suppressed OVA-induced asthma by modulating Th1-/Th2-/Th17-related cytokines; in particular, Th2-related cytokines such as IL-4 and IL-13 were downregulated." (PMID 29151835, 2017). "Phase III studies are underway which should provide further clarification of the potential utility of IL-13 blockade in patients with uncontrolled asthma." (PMID 28721208, 2017). "The role of AMCase, the only IL-13-induced chitinase with chitinase enzymatic activity, in asthma has been conflicting." (PMID 28721208, 2017). "Multiple cell types, including mast cells, eosinophils, basophils, neutrophils, and Th2 lymphocytes, contribute to the pathogenesis of asthma by producing cytokines like interleukin- (IL-) 4, IL-5, and IL-13." (PMID 29062168, 2017). "This common subtype of asthma is characterized by the release of signature cytokines interleukin (IL)-4, IL-5, and IL-13 from cells of both the innate and the adaptive immune systems." (PMID 28721208, 2017). "PIK-294 and dexamethasone combined caused additive suppression of all three cytokines measured from asthma and healthy cells; this additive effect on IL-13 from healthy cells was only apparent at low dexamethasone concentrations." (PMID 27716212, 2016). "As ILC2s are capable of producing IL-13 in response to allergen exposure, it is proposed that ILC2s also contribute to the pathogenesis of these asthma symptoms." (PMID 26965110, 2016). "IL‐13 plays a multi‐faceted role in asthma pathogenesis, triggering goblet cell differentiation and altering smooth muscle contractility." (PMID 27621809, 2016).
asthma (continued). "In fact, IL13 contributes to many key features of asthma [e.g. mucus production, Immunoglobulin E (IgE) synthesis, bronchial fibrosis and AHR] and consequently it is an attractive target for pharmacological intervention." (PMID 26986948, 2016). "Simvastatin reduces IL-13 levels with varying doses in a mouse asthma and bleomycin-induced pulmonary fibrosis model." (PMID 27557561, 2016). "Lungs of humans with asthma have a characteristic expression pattern of inflammatory cytokines, notable amongst those IL-4, IL-6, IL-13, IL-17A and TNF-α50, 51, 52, indicative of Th2 cells and Th17 cells." (PMID 27087690, 2016). "ELISA analysis showed that picroside II down-regulated the levels of Th2-related cytokines (including IL-4, IL-5, and IL-13) and asthma-related mediators, but it up-regulated Th1-related cytokine, IFNγ in BALF." (PMID 27870920, 2016). "Further, considering the inflammatory mediators involved in asthma, kuwanon G significantly decreased the levels of IL-4, IL-5, and IL-13 in the sera and in bronchoalveolar lavage of asthma mice." (PMID 27445433, 2016). "A dominant Th2 response induces several characteristic features of asthma, including eosinophil recruitment, overproduction of Th2-type cytokines (such as IL-4, IL-5, and IL-13), and elevation in the level of IgE." (PMID 27741312, 2016). "Goblet cell hyperplasia, a feature of asthma and other respiratory diseases, is driven by the Th-2 cytokines IL-4 and IL-13." (PMID 27786259, 2016). "Transgenic mice over-expressing IL-13 in their lung develop some of the features of airway inflammation typically observed in asthma." (PMID 27134644, 2016). "Some studies showed that the IL13 rs1800925 C/C genotype was common, and that the T/T genotype was often seen in patients with asthma and allergic dermatitics." (PMID 27167201, 2016). "The OVA-induced airway hypersensitivity model of asthma used here results in eosinophilic inflammation in the lung, pulmonary production of Th2 cytokines (IL-4, IL-5 and IL-13) and serum IgE production." (PMID 27390655, 2016). "Little is known about molecular mechanisms mediated by 1,25D3 in CD8+ T cells, specifically in the conversion to IL-13 production and contributions to asthma pathogenesis." (PMID 26750596, 2016). "As it is known, inflammatory mediators, such as Th2 cells, producing IL-4, IL-5 and IL-13 contribute to not only inflammation but also airway remodeling in asthma." (PMID 27590515, 2016). "TCR stimulation of BAL cells from asthma patients (n = 12) and healthy subjects (n = 11) was performed; IL-13 levels were higher in stimulated asthma compared to healthy cells (means 370 versus 130 pg/ml respectively; p = 0.02)." (PMID 27716212, 2016). "In human, rhinovirus infection induced asthma exacerbation dependent of IL-33 and the production of type 2 cytokines IL-4, IL-5, and IL-13." (PMID 27334012, 2016). "In contrast, miR-21 seems to play a different role in the experimental asthma developed in IL-13 transgenic mice." (PMID 27187364, 2016). "The results found that FLG locus, 5q31 between RAD 50 and IL-13 locus, 6p21 MHC locus and 11q13.5 locus were associated with the co-morbidity of AD and asthma." (PMID 27777593, 2016). "It made sense, therefore, to use periostin levels as a biomarker for anti–IL-13 therapy particularly because some patients with uncontrolled asthma continue to have increased levels of IL-13 in the sputum, despite the use of systemic corticosteroids and ICSs." (PMID 26334389, 2016). "IL-4 and IL-13 can be produced by a variety of cell types of the innate immune system, which plays a crucial role during asthma." (PMID 27716424, 2016). "Regarding IL-13, one of its marked characteristics is contribution to asthma pathogenesis through goblet cell hyperplasia and collagen deposition, which was reduced in Smteg treated mice." (PMID 27454771, 2016).